ALB (albumin)
Diseases named in the same sentence as ALB in open-access papers (continued):
Sharing a sentence is not in itself a finding about the gene and the disease.
cancer (continued). "The clinical characteristics of these donors with CVD are described elsewhere but their baseline ΔS-Cys-Albumin data are provided here for comparison alongside new data from 37 GI cancer patients and 47 cancer-free control donors." (PMID 36182099, 2022). "The albumin-modified IONPs are well-known nanosystems for drug transport, imaging, and for cancer treatment with photodynamic therapy." (PMID 36559265, 2022). "Apart from albumin and other extracellular proteins, necrotic cancer cell debris can also be taken up and utilized as a nutrient source by cancer cells through macropinocytosis." (PMID 35177645, 2022). "Glasgow prognostic score (GPS) is a score that includes the serum level of CRP and albumin reflecting the immunological and nutritional status of cancer patients." (PMID 35756636, 2022). "It should be noted that the effect induced by Zn-Pheide in cancer patients will be probably strictly dependent on their serum albumin level." (PMID 35215347, 2022). "Due to its biological prevalence, biocompatibility, and capacity to target tumor receptors, the use of albumin to improve the delivery of cancer drugs or nanomedicines has been extensively explored." (PMID 36546919, 2022). "This study unveils the spectrum of benefits of pretreatment serum albumin in cancer patients with ICB therapy." (PMID 35393553, 2022). "Systemic inflammation as well as factors produced by malignant tumors can inhibit hepatic albumin production." (PMID 35052870, 2022). "Serum ALB can not only effectively reflect the nutritional status of cancer patients but also be related to the severe liver function caused by inflammatory cytokines." (PMID 35368901, 2022). "Inflammatory indicators such as NLR, LMR and PLR26–29, and nutritional indicators such as albumin and total cholesterol have been used to estimate the prognosis of various types of cancers, including lung cancer." (PMID 35388133, 2022). "IMPLICATIONS FOR PATIENT CARE: Albumin binder conjugation is a promising strategy in the development of FAP-targeted radiopharmaceuticals for treating cancers." (PMID 34593598, 2022). "Further, CAV1 expression was found to directly correlate with nanoparticle albumin conjugate (nab) of paclitaxel sensitivity in pancreas-cancer and NSCLC cells and pancreas-cancer mouse xenograft models." (PMID 35158857, 2022). "Paclitaxel inhibits microtubule depolymerization by inhibiting mitosis in cancer cells, and the PD-L1 antibody, atezolizumab, in combination with albumin–paclitaxel was approved by the FDA as standard therapy for PD-L1-positive TNBC." (PMID 36553667, 2022). "Serum C-reactive protein (CRP) and albumin (ALB) were the most widely recognized indicators to predict prognosis in a variety of cancers, including ESCC." (PMID 35300627, 2022). "Mean albumin levels 3 months before surgery were significantly lower in the malignancy group (2.6 g/dL vs 3.5 g/dL,P value <0.05) while this group was treated with TPN for significantly longer duration (2 vs 0 months, P value <0.05)." (PMID 36449698, 2022). "There are several methods for assessing the nutritional status of cancer, of which serum albumin is one of the most commonly used." (PMID 35729545, 2022). "The primary objective of this observational study was to assess the changes in intraoperative albumin following three major cancer surgeries, while the secondary objective was to assess mid and long-term follow-up and possible parameters affecting survival." (PMID 35329082, 2022). "Preoperatively elevated serum CRP levels are associated with an increased incidence of postoperative complications in cancer patients, while serum albumin is produced in the liver and is the most abundant serum protein." (PMID 34519976, 2022). "There is increasing evidence that combination therapy with nanoparticle albumin-bound paclitaxel (nab-paclitaxel) and programmed cell death protein 1 (PD-1) inhibitor is safe and efficacious in treating many types of malignant tumors." (PMID 35022029, 2022).
cancer (continued). "Hyperfibrinogenemia and decrease albumin levels, which is reflected in the level of plasma fibrinogen and serum albumin (FA), have been demonstrated to be related to the malignant behaviors of various types of cancer." (PMID 36313734, 2022). "A higher reduction in albumin level in cancer cases, from the time of admission to day five (Mean 3.40g/dl to 3.02g/dl), was significantly associated with death during the same hospital stay compared to those discharged (p < 0.001)." (PMID 35350203, 2022). "Deme and Telekes have also reviewed the value of elevated CRP, D-dimer, LDH, and decreased albumin for poor outcomes of cancer patients." (PMID 35173556, 2022). "In clinical application, albumin is often used as a kind of nutrient supplement for cancer patients since it can increase blood volume and maintain plasma osmotic pressure to reduce the weak state of patients." (PMID 35280511, 2022). "The combination of elevated CRP (>10 mg/L) and decreased albumin (<35 g/L) corresponds to higher mGPS, which correlates with systemic inflammation and poor outcome of cancer therapy." (PMID 36232415, 2022). "Subdivision of the cancer patients by albumin status demonstrated that the hypoalbuminemic patient mortality was 68% while the normal albumin patient mortality was 40%." (PMID 35268297, 2022). "It was reported that albumin acts as a nutrient source by cancer cells, and this is the reason why this protein shows accumulation to a greater extent near these cells than the healthy ones." (PMID 36430612, 2022). "In solution, ON-lipid conjugate spontaneously formed micelles, but after in vivo injection it bound to serum albumin and was effectively distributed to cancer cells." (PMID 36411594, 2022). "BMI and albumin have been recognized as essential parameters for evaluating the nutritional status of cancer patients." (PMID 35155556, 2022). "As an important indicator of a patient’s inflammatory and nutritional status, low albumin levels are believed to predict poor outcomes in various cancers, including UTUC." (PMID 35020581, 2022). "Albumin is commonly utilized in people with cancer to assess nutritional quality and systemic inflammation." (PMID 36105255, 2022). "A higher reduction in albumin level in cancer cases, from the time of admission to day five, was significantly associated with death during the same hospital stay compared to those discharged (n=24, 48.9%, p<0.001)." (PMID 35350203, 2022). "Overexpressed FcRn leads to increased albumin recycling, during which the nutrient cargo carried by albumin is released intracellularly and promotes the metabolism and proliferation of cancer cells." (PMID 36339597, 2022). "This was consistent with previous studies identifying that the pre-treatment serum albumin level was a prognostic biomarker in cancer treatment." (PMID 36076157, 2022). "(Notably, even after correction for age, the significant difference in baseline serum ΔS-Cys-Albumin between cancer patients and cancer-free donors remained)." (PMID 36182099, 2022). "PNI, calculated based on total lymphocyte counts and serum albumin levels, reflects the nutritional and immunological status of cancer patients." (PMID 36498630, 2022). "The albumin recycling process was reported to be highly FcRn-dependent and FcRn knockout decreased the metabolic rate of malignant cells in vitro, as well as cancer growth in vivo." (PMID 36339597, 2022). "Secreted protein acidic and rich in cysteine (SPARC), also known as osteonectin or basement membrane 40 (BM40), is the central receptor contributing to the entrapment and catabolism of albumin inside the cancer cell." (PMID 35456562, 2022). "Albumin is an important biochemical marker in palliative cancer care, used for assessment of nutritional status, disease severity and prognosis." (PMID 35629338, 2022).
cancer (continued). "A large number of studies have proved that functionalized liposomes and albumin-based nanocarriers can successfully deliver hydrophobic (or hydrophilic) drugs into cancer cells through different targeting approaches." (PMID 35203695, 2022). "Albumin is considered an important marker for cancer control by stabilizing cell growth and DNA replication." (PMID 35295561, 2022). "The ClinicalTrials.gov website shows that albumin-based nanoparticles have been employed for treating cancer in clinical trials." (PMID 34997888, 2022). "More recently, a comprehensive predictive model for ICB response was developed across 16 different cancer types, which included the features of peripheral blood such as platelets, neutrophil-to-lymphocyte ratio, albumin, and hemoglobin (HGB)." (PMID 36389711, 2022). "In patients across 16 cancer types, there was a similar distribution of pretreatment serum albumin concentrations." (PMID 35393553, 2022). "In recent years, more and more researches have confirmed that low serum albumin are critical poor prognosis predictors in many cancers." (PMID 35392884, 2022). "The serum albumin reflects both the nutritional and the inflammatory status and is considered as a prognostic factor in several cancers." (PMID 35158991, 2022). "Several studies in patients treated with chemotherapy, surgery, targeted therapy, or radiotherapy demonstrated lower OS and PFS in cancer patients with lower albumin levels." (PMID 36533070, 2022). "Univariate analysis identified sex (female), cardiac comorbidity, stage IV disease, low serum albumin, cancer type (gastric/esophageal), hearing deficits, and polypharmacy as risk factors for hospitalization." (PMID 35305099, 2022). "In their prospective study on more than 300 patients, significant associations of low pretreatment serum albumin with worse OS, DFS, and cancer-specific survival (CSS) were observed." (PMID 36297021, 2022). "ALB, a biomarker of nutritional and inflammatory conditions, is often used to evaluate the nutritional status of cancer patients." (PMID 35113866, 2022). "Our study was designed to detect albumin variations in three major cancer surgeries: ovarian debulking (DBK), major abdominal gastrointestinal surgery (ABD), and major cervico-facial, or ear, nose and throat cancer surgery (ENT)." (PMID 35329082, 2022). "The mGPS was designed to predict survival in cancer patients using only C-reactive protein and albumin." (PMID 35215419, 2022). "The PNI is based on lymphocyte count and albumin level, which are significantly closely related to the prognosis of cancer patients, and a low PNI indicates increased inflammatory reaction and poor nutritional status." (PMID 36329394, 2022). "The present findings support the feasibility of using EGFR as the therapeutic molecular target and albumin as the carrier for cancer targeted therapy." (PMID 35416106, 2022). "Intrahepatic biliary obstruction, stage IV cancer, pre-endoscopic serum albumin, TB improvement of more than 50% from baseline within 2 weeks after stenting, and chemotherapy after ERCP were associated with 90-day mortality." (PMID 36147905, 2022). "The mechanism behind this discrepancy is not clear but seems to be driven by modestly elevated levels of ΔS-Cys-Albumin in cancer patient serum versus serum from the other two patient cohorts." (PMID 36182099, 2022). "Reduced levels of ALB, an important nutritional biomarker, are closely related to persistent systemic inflammatory responses that affect malignant tumor progression." (PMID 36428725, 2022). "Many inflammation-based scores such as the ratio of C-reactive protein to albumin are related to prognosis of several cancers, including HNC." (PMID 35954360, 2022). "Albumin can also be functionalized using targeting ligands to specifically address the overexpressed receptors on the surface of cancer cells, i.e., EGFR, folate receptors (FR) or interleukin-13 alpha 2 receptor (IL13Rα2)." (PMID 36234629, 2022).
cancer (continued). "Although the C-reactive protein to albumin ratio (CAR) has been repeatedly reported to be related to poor prognosis in various cancers, including pancreatic, gastric, lung, and esophageal cancer, its role in TETs remains to be elucidated." (PMID 36397047, 2022). "This study was designed, for the first time, to load Ap into chitosan to improve its hydrophobicity and then it was coated with albumin-folic acid to increase its stability and bioavailability and to target cancer cells." (PMID 35745733, 2022). "We previously demonstrated that linking peptide antigens to amphiphilic lipid tails promotes albumin-mediated transport into lymphatics after parenteral injection, thereby enhancing antigen-specific T cell responses that are critical for cancer immunity." (PMID 35857825, 2022). "Laboratory parameters like albumin are inexpensive and readily available measures of cancer patients’ nutritional status." (PMID 36533070, 2022). "The decrease in serum ALB was present in all three types of major cancer surgeries but was less pronounced in major cervicofacial surgeries." (PMID 35329082, 2022). "As a natural ligand carrier, albumin has shown remarkable promise as a carrier for anti-cancer agents to promote their accumulation within tumors." (PMID 35164144, 2022). "The fusion of multiple antibodies to albumin enabled to overcome the resistance of cancer against single antibody, as well as improving their pharmacokinetics." (PMID 35456562, 2022). "Effects of age, gender, and race on baseline ΔS-Cys-Albumin values in the GI cancer patients and cancer-free control donors were also assessed." (PMID 36182099, 2022). "The nutritional risk index (NRI), calculated using the patient’s height, weight, and serum albumin level, has proven to be a more reliable evaluation of nutrition status than BMI and serum albumin in many types of cancer." (PMID 36145159, 2022). "For patients with advanced cancer, the albumin decrease because of its consumption due to cancer cachexia." (PMID 35445073, 2022). "This is particularly of interest in cancer disease, as albumin nanoparticles tend to be accumulated at the tumors." (PMID 35267507, 2022). "A systematic review reported the predictive ability of PA for nutritional status in advanced cancer patients and found that low PA was related to worse nutritional status as assessed by BMI, serum albumin level, transferrin, and fat-free mass." (PMID 36615707, 2022). "Due to these premises, the roles of albumin and fibrinogen as potential biomarkers in cancer have been investigated in different studies." (PMID 36295649, 2022). "Within CVD patients and cancer-free controls, ΔS-Cys-Albumin in K2EDTA plasma was higher than that of serum in matched collections; and in the cancer-free controls, it was also higher than LiHep plasma." (PMID 36182099, 2022). "Previous studies found that the peripheral blood platelet and fibrinogen are significantly related to the progress of malignant tumors, while the development of malignancies is related to the decrease in the hemoglobin and albumin." (PMID 36387243, 2022). "In human medicine, several studies have recently shown the prognostic potential of the CRP/ALB ratio as a prognostic factor in cancer patients with different types of solid tumors." (PMID 35873678, 2022). "There are studies which show the relationship of fibrinogen and albumin individually with cancer prognosis in many cancers." (PMID 36496365, 2022). "Serum ALB is one of the most popular ways to evaluate cancer patients' nutritional status among the several available approaches." (PMID 36531036, 2022). "ΔS-Cys-Albumin in freshly collected and processed samples from cancer patients, however, was the same across all three matched matrices." (PMID 36182099, 2022). "When the SPARC receptor recognizes and binds to albumin, the complex is endocytosed to cancer cells and then undergoes degradation." (PMID 35456562, 2022).
cancer (continued). "The protein Cav-1 responsible for the formation of caveolae is upregulated in cancer cells, and since endocytosis of albumin is mainly mediated through caveolae, the accumulation of albumin in cancer sites is further enhanced." (PMID 34298666, 2021). "Abraxane, is the albumin nanoparticles to deliver paclitaxel, which has been approved in clinical application of cancer treatment by FDA." (PMID 33407570, 2021). "As known, hemoglobin levels have a prognostic role in cancers and are predictive for response to various anti-cancer therapies, especially when combined with albumin, lymphocyte, and platelet levels." (PMID 34820323, 2021). "AAPR appeared to perform better than ALP and ALB alone in predicting the survival outcomes of cancer patients." (PMID 34539891, 2021). "The decrease of albumin reduces the body’s ability to cope with variable stresses, such as malignant tumors and surgery." (PMID 34381731, 2021). "Note that in the original dataset, more patients in the perioperative pRBC transfusion group tended to have lower preoperative hemoglobin and albumin levels, less laparoscopic surgery, longer anesthesia time and more advanced cancer." (PMID 34771598, 2021). "Prognostic nutritional index (PNI), an evaluation index indicating immunological and nutritional status in patients defined as serum albumin plus lymphocyte count, has been considered of unique prognostic values in various cancers." (PMID 33718126, 2021). "Many studies are being performed to develop effective carriers for controlled cytostatic delivery wherein albumin is a promising material due to its tendency to accumulate near cancer cells." (PMID 34442909, 2021). "For the treatment of these cancers, in the present study, bovine serum albumin (BSA) nanoparticles (ABNs) were prepared by desolvation method using ethanol." (PMID 34208533, 2021). "In the interstitial space, this complex binds to an extracellular matrix protein called SPARK, increasing the shelf life of drug-containing albumin in the extracellular space and releasing paclitaxel over a long period of time in the vicinity of cancer cells." (PMID 34051806, 2021). "Based on its inherent biochemical and biophysical properties, the albumin is considered an ideal platform for cancer therapeutic administration." (PMID 33920299, 2021). "For example, the great success of abraxane (albumin-particle bound paclitaxel) in cancer medicine encourages numerous other different paclitaxel-based nanomedicine waiting for clinical trials." (PMID 34209111, 2021). "It has been proven that the conjugation of peptides and proteins with a polymer of this type (1.5 kDa) allows extending the circulation time of anti-cancer proteins and peptides by binding the conjugates to plasma albumin." (PMID 34207137, 2021). "Due to the high accumulation of serum albumin in cancer tissues, there are other researches working towards the same goal." (PMID 34771316, 2021). "In the present work, we described the preparation and characterization of size and shape-tuned of two novel conjugates based on gold nanoparticles (AuNP), fluorine-labeled albumin, fluorescent dye, and with decorated drugs/agents involved in cancer therapy." (PMID 33451058, 2021). "It is generally known that low levels of serum albumin and lymphocytes promote inflammatory tumor development and the spread and metastasis of cancer." (PMID 33859986, 2021). "In this study, we also noticed that the cutoff value of albumin (39 g/L) is greater than previous studies of other cancers." (PMID 34445989, 2021). "The impact of albumin-to-alkaline phosphatase ratio (AAPR) on prognosis in cancer patients remains uncertain, despite having multiple relevant studies in publication." (PMID 33685425, 2021). "Serum albumin-to-alkaline phosphatase ratio (AAPR) has been proven to be a prognostic indicator of many malignant tumors." (PMID 33959511, 2021).